PNRC1 (proline rich nuclear receptor coactivator 1)
Description:
Nuclear receptor coactivator. May play a role in signal transduction.
Synonyms: PROL2; B4-2; PRR2; PNAS-145
Tractability: PROTAC: ubiquitination databases record sites on it.
Gene: Protein-coding gene on chromosome 6 (89,080,751 to 89,085,160, forward strand). Ensembl gene ENSG00000146278.
Subcellular location: Nucleus
Subcellular location (Human Protein Atlas): Nucleoli; Nucleoplasm
Gene Ontology:
Molecular function: protein binding
Biological process: nuclear-transcribed mRNA catabolic process
Cellular component: nucleus
Genetic constraint (gnomAD): Loss-of-function variants: 6 observed, 16.56 expected, observed/expected ratio (o/e) 0.36, 90% interval 0.2 to 0.71. The synonymous counts are far from expectation, so gnomAD's model fits this gene poorly and the ratio says little. Missense variants: 482 observed, 384.89 expected, observed/expected ratio (o/e) 1.25, 90% interval 1.16 to 1.35. Synonymous variants: 199 observed, 155.78 expected, observed/expected ratio (o/e) 1.28, 90% interval 1.14 to 1.44.
Homologues: Orthologues: chimpanzee PNRC1 (99% identical), dog PNRC1 (90% identical), rabbit PNRC1 (90% identical), pig PNRC1 (88% identical), guinea pig PNRC1 (87% identical), mouse Pnrc1 (76% identical), rat Pnrc1 (76% identical), zebrafish pnrc1 (18% identical), Drosophila melanogaster aqz (14% identical). Paralogues in human: PNRC2 (16% identical).
Diseases named in the same sentence as PNRC1 in open-access papers:
PNRC1 is named in the same sentence as 17 diseases in open-access papers, as found by Europe PMC text mining. Sharing a sentence is not in itself a finding about the gene and the disease. The quoted sentences say what the papers report.
brain cancer (1 paper, 2024). A primary or metastatic malignant neoplasm affecting the brain. "(B) Negative correlation between the mRNA levels of CTGF and PNRC1 in brain cancer cell lines (n = 83) and thyroid cancer cell lines (n = 17)." (PMID 39046443, 2024).
breast carcinoma (1 paper, 2024). "Next, we confirmed the significantly downregulated mRNA expression of AJUBA, WTIP, SAMD4A, and NOCT and moderately increased expression of PNRC1 in YAP/TAZ knockdown HCT116 cells by qPCR analysis; this pattern was also observed in A549 lung cancer cells and MDA-MB-231 breast cancer cells." (PMID 39046443, 2024).
cholesteatoma (1 paper, 2021). A pathologic process characterized by the proliferation of keratinizing squamous epithelium resulting in the accumulation of keratin and cells in the middle ear and/or mastoid. "Compared to the paired retroauricular skin sample, ten cholesteatoma tissues displayed significant downregulation of PNRC1." (PMID 34825000, 2021). "We found that miR-199a promoted keratinocyte proliferation, migration, and invasion in cholesteatoma by directly targeting PNRC1." (PMID 34825000, 2021). "However, more assays concerning the function of PNRC1 in cholesteatoma will be needed to verify this regulation." (PMID 34825000, 2021). "Interestingly, we found that PNRC1's expression was downregulated in cholesteatoma tissues and PNRC1's expression increased in HaCaT cells transfected with the miR-199a inhibitor and PNRC1's expression decreased in HaCaT cells transfected with miR-199a mimics at the mRNA level." (PMID 34825000, 2021).
colorectal cancer (1 paper, 2024). A primary or metastatic malignant neoplasm that affects the colon or rectum. "PNRC1 attenuates the oncogenic function of YAP in colorectal cancer (CRC)." (PMID 39046443, 2024). "Mechanistically, both transcriptional activation of the P-body-related genes SAMD4A, AJUBA, and WTIP and transcriptional suppression of the tumor suppressor gene PNRC1 are involved in enhancing the effects of YAP/TAZ on P-body formation in colorectal cancer (CRC) cells." (PMID 39046443, 2024). "As a direct YAP/TAZ target gene, PNRC1 functions as a critical effector in YAP-induced biogenesis of P-bodies and tumorigenesis in colorectal cancer (CRC)." (PMID 39046443, 2024).
COVID-19 (1 paper, 2023). A disease caused by infection with severe acute respiratory syndrome coronavirus 2. "In the present study, we succeeded in identifying 3 key genes, DDIT3, MAFF, and PNRC1, which are possibly involved in the development of both OA and COVID-19 and have high diagnostic value for OA and COVID-19." (PMID 37283761, 2023). "Collectively, these results suggest that DDIT3, MAFF, and PNRC1 play important roles in OA and COVID-19 pathogenesis, while STX11 lacks specificity." (PMID 37283761, 2023). "In contrast, the role of PNRC1, a marker with high diagnostic value for both OA and COVID-19, has not been investigated in OA and COVID-19, which provides a new perspective to study the potential connection and common pathogenesis between OA and COVID-19." (PMID 37283761, 2023). "In addition, we screened 3 key genes, DDIT3, MAFF, and PNRC1, and uncovered that key genes are possibly involved in the pathogenesis of OA and COVID-19 through high expression in neutrophils." (PMID 37283761, 2023). "As shown in the UMAP and violin plots, in COVID-19 patients, DDIT3 was highly expressed in neutrophils and cDC cells, MAFF was highly expressed in neutrophils and GZMK NK cells, and PNRC1 was highly expressed in almost all immune cells and blood cells." (PMID 37283761, 2023). "In this study, we identified 26 common genes between OA and COVID-19 by WGCNA and screened three key genes DDIT3, MAFF, and PNRC1 using machine learning algorithms." (PMID 37283761, 2023). "Comparing the results of the analysis with those of the HPA database, we found that the expression of DDIT3, MAFF, and PNRC1 in immune cells was the same as normal, indicating that the expression pattern of key genes in immune cells did not change during the progression of COVID-19." (PMID 37283761, 2023).
cutaneous melanoma (1 paper, 2022). A primary melanoma arising from atypical melanocytes in the skin. "Lastly, we treated three cutaneous melanoma cell lines with Nutlin-3 for 24 h and investigated the mRNA expression of RFX7, RFX5, PNRC1, PDCD4 and CDKN1A as positive control." (PMID 36139642, 2022).
liver cancer (1 paper, 2024). An epithelial or non-epithelial malignant neoplasm that arises from the liver. "Moreover, hemizygous deletion of the 6q15 locus, where PNRC1 is located, occurs in multiple cancers, including prostate, pancreatic, breast, and liver cancers." (PMID 39046443, 2024).
medulloblastoma (1 paper, 2023). A malignant, invasive embryonal neoplasm arising from the cerebellum. "Of these seven genes (LTBP1, MAP1A, MBNL2, LGALS1, PNRC1, DAB2, and PLAAT3), only one, LGALS1, had been researched previously in relation to medulloblastoma, where it is up-regulated in MBSHH patients and activated by the SHH signalling pathway." (PMID 36831428, 2023).
tumor (7 papers, 2015 to 2025). "We further confirmed the decreased mRNA level of PNRC1 in CRC by qPCR analysis of 16 CRC tissues with paired normal mucosal tissues; this finding implies that PNRC1 is a potential tumor suppressor also in CRC." (PMID 39046443, 2024). "The expression analysis of key genes (PNRC1, HERPUD1, TP53INP2, Tob1, and SAT1), which is typically silenced in various tumour tissues and associated with poor prognosis and short survival time, revealed their upregulation upon 24 h treatment with L1." (PMID 39861074, 2024). "Intriguingly, both serum starvation and culture at a high cell density dramatically increased the expression of PNRC1, consistent with the tumor suppressor function of PNRC1." (PMID 39046443, 2024). "Recently, a study exploring new TSGs based on hemizygous deletions in multiple cancers revealed that PNRC1 is a novel tumor suppressor gene." (PMID 39046443, 2024). "To verify the tumor-suppressive effect of PNRC1 on YAP in CRC in vivo, we performed a xenograft assay by subcutaneously injecting HCT116 cells into nude mice." (PMID 39046443, 2024). "Frequent CN deletions between axillary lymph node metastasis and BC primary tumours were revealed, including aberrations at 6q15-16, containing the gene PNRC1 (a putative tumour suppressor)." (PMID 26391647, 2015). "This translocation of DCP1A/DCP2 also leads to disassembly of P-bodies; thus, PNRC1 could also inhibit tumor cell proliferation by disrupting P-body formation." (PMID 39046443, 2024). "Overall, these results indicate that YAP promotes tumorigenesis by downregulating PNRC1 expression and that reexpression of PNRC1 suppresses YAP-driven tumor growth." (PMID 39046443, 2024). "Most strikingly, our analysis revealed a seven-gene drug-tolerant signature in all four drug-tolerant cell lines, irrespective of chemotherapeutic treatment, parental cell line and tumour subgroup—LTBP1, MAP1A, MBNL2, LGALS1, PNRC1, DAB2 and PLAAT3." (PMID 36831428, 2023). "It has been shown that PNRC1 inhibits RAS- and MYC-driven tumor cell proliferation." (PMID 39046443, 2024). "By reexpression of PNRC1 or knockdown of P-body core genes (DDX6, DCP1A, and LSM14A), we determined that disruption of P-bodies attenuates cell proliferation, cell migration, and tumor growth induced by overexpression of YAP5SA in CRC." (PMID 39046443, 2024).
cancer (6 papers, 2019 to 2025). A tumor composed of atypical neoplastic, often pleomorphic cells that invade other tissues. "PNRC1 is a newly identified tumor suppressor gene whose expression is frequently downregulated in cancer." (PMID 39046443, 2024). "We only chose PNRC1 for the following study, because miR-199a has a cancer-promoting effect in our study; then, we need to find a target gene that is negatively correlated with miR-199a." (PMID 34825000, 2021). "Indeed, we and others have shown that PNRC1 is generally expressed in normal cells but is pervasively deleted and down-regulated in cancer." (PMID 31533350, 2019). "Thus, our study reveals a YAP–P-body positive regulatory axis in CRC, which exposes the vital role of YAP/TAZ in the biogenesis of P-bodies in tumors and implies that reexpression of PNRC1 or disruption of P-bodies is a potential therapeutic strategy for cancers with active YAP." (PMID 39046443, 2024). "A set of genes, including PNRC1, HERPUD1, TP53INP2, Tob1, and SAT1, were downregulated in patients with different cancer types, and their decreased expression was correlated with poorer prognosis and shorter survival time." (PMID 39861074, 2024). "Due to the inhibitory effects of PNRC1 on P-body formation and the YAP-induced oncogenic phenotype, we evaluated whether enhanced P-body formation plays a vital role in YAP-driven cancer cell proliferation and migration." (PMID 39046443, 2024). "However, although pieces of evidence for promoter hypermethylation in cancer have emerged for both NUDT16 and PNRC1, the molecular mechanisms by which oncogenes may regulate nucleolar decapping are still unknown." (PMID 31533350, 2019).
infection (1 paper, 2021). The state of being infected such as from the introduction of a foreign agent such as serum, vaccine, antigenic substance or organism. "Interestingly, in this present study, whereas PCPEC displayed a strong inflammatory response to infection, genes attributed to hypoxia were found to play a more prominent role during infection in HIBCPP cells (including ZFP36L1, MXI1, KLHL24, PNRC1, CDKN1C, and DUSP2)." (PMID 33763387, 2021).
PNRC1 also shares sentences with these, for which no sentence is quoted: lung carcinoma (1 paper); lupus (1); lymphoma (1); melanoma (1); thyroid cancer (1); uveal melanoma (1).